RNU1-70P (RNA, U1 small nuclear 70, pseudogene)
Gene: Small nuclear RNA gene on chromosome 3 (170,994,870 to 170,995,033, reverse strand). Ensembl gene ENSG00000199488.
Homologues: Orthologues: chimpanzee U1 (96% identical), macaque U1 (92% identical), mouse Gm25796 (64% identical). Paralogues in human: RNU1-89P (85% identical), RNU1-1 (84% identical), RNU1-2 (84% identical), RNU1-27P (84% identical), RNU1-28P (84% identical), RNU1-3 (84% identical), RNU1-4 (84% identical), RNVU1-18 (84% identical), RNVU1-29 (84% identical), U1 (84% identical), RNU1-19P (84% identical), RNVU1-28 (84% identical), and 134 more.